VEGFA (vascular endothelial growth factor A)
Diseases named in the same sentence as VEGFA in open-access papers (continued):
Sharing a sentence is not in itself a finding about the gene and the disease.
glioblastoma (continued). "We previously showed that the disruption of the NRP1/Plexin-A1 dimer suppresses vascular endothelial growth factor type A (VEGFA)-induced migration of glioblastoma U-118MG cells." (PMID 31652529, 2019). "These authors showed that FAT1 is associated with HIF-1α expression, as well as with its targets PGK1 (Phosphoglycerate kinase 1) and VEGFA in human glioblastoma samples." (PMID 31010154, 2019). "The glioblastoma cells secrete vascular endothelial growth factor A (VEGF-A), which induces neovascularization and the formation of a highly dysfunctional vascular system in the tumor." (PMID 29156610, 2017). "Vascular endothelial growth factor A (VEGF) is considered a major pro-angiogenic mediator in glioblastoma multiforme (GBM), the most common and aggressive type of primary brain tumours in adults." (PMID 25680186, 2015). "In addition, YTHDF2 can maintain oncogene MYC and VEGFA transcripts in glioblastoma stem cells, thereby offering a therapeutic opportunity in glioblastoma." (PMID 40986143, 2025). "Angiogenesis is a prominent pathological feature of glioblastoma and is mainly attributed to autocrine and paracrine secretion of vascular endothelial growth factor-A (VEGF-A), further up-regulating the VEGF signal transduction pathway, leading to its overexpression." (PMID 39015784, 2024). "Finally, we performed immunohistochemistry and immunofluorescence staining on glioblastoma samples from the high‐ and low‐risk score groups, confirming the higher expression of CD99, EGFR and VEGFA in the high‐risk group." (PMID 38687049, 2024). "The observed regulation of VEGFA by miR-10b under hypoxic conditions led us to further explore how hypoxia might influence the distribution of miRNAs in the glioblastoma cell line medium, particularly regarding exosomal signaling." (PMID 39063226, 2024). "Previously, we have screened 59 differentially expressed miRNAs and 419 mRNAs in the glioblastoma samples that have been compared to the peritumoral tissues using bioinformatics analyses, which included miRNA-383-5p and vascular endothelial growth factor A (VEGFA)." (PMID 37592783, 2023). "CircRNA SMARCA5 binds to SRSF1 protein to modulate VEGFA mRNA splicing in glioblastoma multiforme." (PMID 36800233, 2023). "Additionally, the decrease in glioblastoma angiogenesis after KDELC2 knockdown depended on the low expression of VEGFA, VEGFR1, and CD31." (PMID 37107298, 2023). "There, genes with a higher expression in glioblastoma compared to astrocytoma were VEGFA, 4EBP1, CCL2, PLAU (uPA), CXCL8 (IL8), CXCL10 (IP10), CASP8, HGF, LIF, CD40, CDCp1, TNFRSF11B (OPG), CD274 (PD-L1), IL6, CXCL1, CCL20 (MIP3α), CCL8 (MCP2), CD244, MMP1, TNFRSF9, CXCL6, MMP10, FGF5)." (PMID 35301393, 2022). "Similarly, VEGFA mRNA can also be directly modulated by miR-205 in glioblastoma cells or ARPE-19 cells." (PMID 35624680, 2022). "Finally, independently of the immune system, the involvement of MMP9 in VEGFA release was also reported in a preclinical model of glioblastoma, highlighting its potential central role in the initiation and promotion of angiogenesis." (PMID 34980260, 2022). "Also, YTHDF2 was found to stabilize MYC and VEGFA transcripts in glioblastoma stem cells in an m6A-dependent manner." (PMID 35526051, 2022). "On the basis of these preclinical results, we can hypothesize that MMP9 released by tumor-infiltrating neutrophils may increase VEGFA availability in the glioblastoma microenvironment, exceeding the ability of bevacizumab to trap it." (PMID 34980260, 2022). "Hsa_circ_0001445 could regulate VEGFA mRNA through binding to SRSF1 in glioblastoma, while in HCC, it sponged miR-17–3p and miR-181b-5p to induce the expression of TIMP3 in order to inhibit growth and metastasis." (PMID 34992634, 2021).
glioblastoma (continued). "The glioblastoma findings support our observations regarding the relevance of EndoMT and possible mechanism for resistance to anti-VEGFA in pathologic neovascularization, and suggest further exploration of combination therapy with novel EndoMT inhibitors and anti-VEGFA in neovascular disorders." (PMID 32917003, 2020). "It was previously reported that Sp1 could directly promote the expression of VEGFA, and that miR-212-3p could inhibit angiogenesis and proliferation of glioblastoma, and ZLM-7 could increase the expression of miR-212-3p in BC cell lines." (PMID 33187481, 2020). "Steroid-sparing treatments for peritumoral edema that target the vascular endothelial growth factor-A (VEGF-A) pathway are standard-of-care agents in progressive glioblastoma and under clinical development in patients with MBM with concerns about safety and efficacy (clinicaltrials.gov NCT02681549)." (PMID 33552976, 2020). "During glioblastoma treatment, the pharmaceutical monoclonal antibody to vascular endothelial growth factor A, bevacizumab, has improved the quality of life and delayed progression for several months, but has not (or only marginally) prolonged overall survival." (PMID 30274295, 2018). "We also noticed that the transcription of key genes involved in inflammation, proliferation, angiogenesis and extracellular matrix remodelling (including MMP2, HIF1A, IL1B, IL1A, IL1R1, MMP2, VEGFA), processes vital to glioblastoma development, were down-regulated by RND3 knock-down." (PMID 26132659, 2015). "VMP1 promotes angiogenesis in glioblastoma (GBM) through VEGFA‐VEGFR2 signaling and activation of endothelial cells." (PMID 41589276, 2026). "The VEGF signalling network, mediated by VEGFA‐VEGFR1/VEGFR2/VEGFR1R2, was primarily concentrated between high‐risk scoring TAMs, pericyte and endothelial cells, suggesting that high‐risk scoring TAMs may promote angiogenesis in glioblastoma." (PMID 38687049, 2024). "Exosomes derived from hypoxic glioblastoma cell line U87 promotes the proliferation of brain microvascular endothelial cells and enhances the permeability through vascular endothelial growth factor-A (VEGF-A) by reducing the expression of claudin-5 and occludin." (PMID 34365576, 2022). "It has been found to be downregulated in unaffected brain parenchyma, as compared to human glioblastoma tissue, where it appears to influence tumor angiogenesis by stimulating the formation of the proangiogenic form of the vascular endothelial growth factor A (VEGFA)." (PMID 35056447, 2022). "Besides EMP1, EMP2 has been shown to be upregulated in more than 70% of both serous and endometrioid ovarian cancers, and to enhance tumor growth of glioblastoma by promoting angiogenesis, partially by increasing vascular endothelial growth factor-A expression in glioblastoma cells." (PMID 29867202, 2018). "KIF4A promotes malignant progression of glioblastoma and transmission of TMZ resistance in the tumor microenvironment through the HIF1A/VEGFA axis." (PMID 41084153, 2025). "Genes such as VEGFA, PD-L1, PIK3CD, PRMT5, and STAT3 emerge as central nodes driving glioblastoma progression and therapeutic resistance." (PMID 41179304, 2025). "Clusters 1–3 represented glioblastoma cells expressing Nestin, Ki67, EGFR and VEGFA, with cluster 1 showing the most aggressive signature and highest inferred fraction of cells in the G2M cell cycle phase." (PMID 39304781, 2024). "Mechanistically, we revealed that FBXO22 stimulates the activation of the HIF-1α-VEGFA pathway by directly binding and mediating VHL ubiquitination degradation and promoting the malignant progression of glioblastoma." (PMID 38519492, 2024). "By increasing the activity of the VEGFA-VEGFR2 pathway, ARL13B stimulates angiogenesis and glioblastoma tumor growth." (PMID 38892305, 2024).
glioblastoma (continued). "A critical protein that facilitates new blood vessel formation is vascular endothelial growth factor-A (VEGF-A), therefore, bevacizumab, a medication that specifically targets VEGF-A has been approved for treatment of recurrent glioblastoma." (PMID 36765787, 2023). "CircSMARCA5 acts as the sponge for SRSF1 in glioblastoma multiforme (GBM), regulates the splicing of VEGFA, and affects angiogenesis." (PMID 35806027, 2022). "In glioblastoma stem cells, the m6A modification of MYC and VEGFA (Vascular endothelial growth factor A) was found to be upregulated." (PMID 35682599, 2022). "Anti-VEGFA drugs could benefit proneural glioblastoma (GBM) patients, and anti-PD-1 drugs seem effective for BRAF mutated GBM." (PMID 34079802, 2021). "In glioblastoma, in contrast to its proposed role, YTHDF2 was shown to stabilize MYC and VEGFA to maintain the oncogenic phenotype of glioblastoma stem cells." (PMID 33795663, 2021). "Our study shows the cells grown in 3D-GMH with serum overexpress and secrete CXCL1, CXCL5, IGFBP2, PTX3, THBS1, VEGFA, and VCAM1—all genes expressed in perivascular or perinecrotic zone of glioblastoma tissues that are hotspots for immune cells." (PMID 34489494, 2021). "The pathways with the highest p-values were signaling pathways in glioblastoma, pathways regulating PI3K-Akt, Hippo, VEGFA-VEGFR2, Ras, and EGFR signaling (p-values < 10−10)." (PMID 33348918, 2020). "Bevacizumab, an antibody targeting vascular endothelial growth factor A (VEGF), has been proposed as an active drug, given that glioblastoma is characterized by an abnormal tumor vasculature fueled by pro‐angiogenic stimulation from VEGF overexpression." (PMID 32133779, 2020). "Additionally, current evidence shows that circRNA SMARCA5 (circ-SMARCA5) can bind to serine and arginine rich splicing factor 1 (SRSF1) to regulate VEGFA pathway in glioblastoma multiforme (GBM) cells." (PMID 31937318, 2020). "Data from TCGA database indicated that VEGFA is also expressed highly in kidney renal clear cell carcinomas (KIRC), ovarian serous cystadenocarcinomas (OV) and glioblastoma (GBM), as well as HNSCC." (PMID 31198634, 2019). "Fn14 was found to be co-expressed with IGFBP2 and 3 and VEGFA, IFNγR2, TNFR1A and IGFBP2 and lamin A, suggesting a possible role of this receptor in glioblastoma angiogenesis." (PMID 24376672, 2013). "In addition, higher expression levels of MMP9, TERT, VEGFA, ZDHHC18, CHEK2, and ADM elevate the probability of predicting glioblastoma." (PMID 40867242, 2025). "Also, dual inhibition of Ang-2/VEGF with a bispecific anti-Ang2/VEGFA antibody (CrossMab, A2V) prolongs the survival of patients and animal models of glioblastoma and sarcoma." (PMID 39003350, 2024). "One exception is glioblastoma, where the combination of anti-PD-1 and anti-VEGFA was not better than administering anti-VEGFA as a single agent." (PMID 35577211, 2022). "For instance, circSMARCA5 could regulate VEGFA mRNA splicing and angiogenesis through the binding of SRSF1 in glioblastoma multiforme." (PMID 34034688, 2021). "Similarly, enhanced invasiveness and growth capacity of glioblastoma and RCC cells have been demonstrated following VEGFA inhibition." (PMID 32775327, 2020). "The antiangiogenic therapies used until now, which mostly target the VEGF signaling pathway and include Bevacizumab (targeting VEGFa), have shown no benefit to overall survival for glioblastoma patients." (PMID 32054826, 2020). "In vitro, they demonstrated that severe hypoxia induces the expression of FAT1 and that the depletion of endogenous FAT1 under hypoxia induces a decrease in HIF-1α, CAIX, GLUT1, VEGFA, MCT4, HK2, BNIP3, and REDD1, as well as a decrease in glioblastoma cell invasion." (PMID 31010154, 2019).
glioblastoma (continued). "Regarding the first signature network component, hsa-mir-137, hsa-mir-330, hsa-mir-149, hsa-mir-107, hsa-mir-181b were among the miRNAs whose experimentally validated targets (such as CTBP1, CDC42, CDK6, E2F1, VEGFA, AKT1, KAT2B) affect the pathways which play a crucial role in glioblastoma biology." (PMID 28045122, 2017). "Using transcriptomic data from the BELOB phase II trial, which compared lomustine versus lomustine plus bevacizumab in recurrent glioblastoma, we confirmed that CSF3 expression was overexpressed in mesenchymal tumors and correlated with VEGFA expression (see eFigure 5 in the Supplement)." (PMID 27487142, 2016). "In glioblastoma (GBM), pharmacological inhibition of FTO (e.g., using FB23-2) increases m6A modification on the target gene VEGFA, downregulating its expression and impairing DNA damage repair (e.g., sustaining γH2AX foci and reducing Rad51 recruitment)." (PMID 40823093, 2025). "Key members of the gene network,including vascular endothelial growth factor A (VEGFA),epidermal growth factor (EGF), and the catalytic subunitA of phosphatidylinositol-4,5-bisphosphate-3-kinase(PIK3CA), have been identified as important genetic markersof glioblastoma involved in angiogenesis." (PMID 39944803, 2024). "Although bevacizumab, an anti-VEGFA antibody, has shown efficacy by prolonging PFS in clinical trials for glioblastoma, it fails to affect overall survival." (PMID 31234870, 2019). "However, the relationship between VEGFA and KLF4 genes have no statistical significance in glioblastoma." (PMID 31198634, 2019).
Hypertension (703 papers, 2007 to 2026). The presence of chronic increased pressure in the systemic arterial system. "In this study, we found that rs3025010 within the VEGFA gene was associated with hypertension, and hypertension subjects with C/T and C/C genotypes at rs3025010 had lower SBP and DBP levels." (PMID 32257424, 2020). "We found that the distribution of genotypes at rs833061, rs3025010, and rs699947 within the VEGFA gene and the distribution of alleles at rs3025010 in hypertension subjects were different from those in controls." (PMID 32257424, 2020). "Hypertension and polymorphisms affecting the VEGFA pathway have shown some predictive value of bevacizumab benefit, although their limitations included lack of standardization, and inconsistent effect among studies." (PMID 26921265, 2016). "In summary, our findings suggest that rs3025010 in VEGFA is associated with hypertension." (PMID 32257424, 2020). "The most frequent trAEs were hypertension or proteinuria, which were also commonly observed upon anti-VEGFA monotherapy and are generally manageable." (PMID 35577211, 2022). "The results showed that the distribution of rs833061, rs3025010, and rs699947 genotypes in the VEGFA gene were significantly different between the hypertension group and the control group (P < 0.05)." (PMID 32257424, 2020). "For this reason, bevacizumab, a monoclonal antibody targeting vascular endothelial growth factor A (VEG-F) is effective for ascites reduction, but this drug also has a significant toxicity profile including severe hypertension and bowel perforation that often precludes its use." (PMID 39276533, 2024). "In CD8 memory T cells, several pathways associated with mitochondrial oxidative metabolism, vascular endothelium, and immune inflammation were activated during hypertension; examples include VEGFA-VEGFR2 signaling, aerobic glycolysis, and the canonical NF-kB pathway." (PMID 37009484, 2023). "Based on the results of the network analysis and molecular docking, we found that AKT1, VEGFA, eNOS, ICAM-1, PTGS2, and ALB may also be associated with the potential effects of GZD on hypertension." (PMID 33906674, 2021). "Other common target genes were vascular endothelial growth factor A (VEGFA), forkhead box 01 (FOX01), and jun proto-oncogene (JUN) for miR-532-5p and miR-133a-3p, which were associated with cancer and mechanisms related to inflammation, hypertensive disease, and myocardial ischemia (VEGFA and JUN)." (PMID 34440025, 2021). "The occurrence of hypertensive disorder complicating pregnancy can be caused by the decrease of the expression of MMP9 in the network, and AKT1, ESR1, FOS, VEGFA and other proteins play an important role in the pathogenesis of hypertensive disorder complicating pregnancy, such as preeclampsia." (PMID 34062719, 2021). "Four intermediate concepts connected HET-0016 and ADPKD: VEGFA, hypertensive disease, renal blood flow, and systolic pressure, which suggests that HET-0016 may be used to treat the hypertensive component of ADPKD." (PMID 31000794, 2019). "Additionally, it has been reported that MC-LR could down-regulate VEGFA and TGF-β expression via the AKT/m-TOR/HIF-1α pathway, which was linked to hypertension." (PMID 39728800, 2024). "In addition, previous studies in humans reported that polymorphisms of genes such as VEGFA, VEGFR-2, ET-1, and eNOS might predispose to hypertension after Su treatment." (PMID 32698382, 2020). "The increased value of VEGFA, accompanied by decreased NO, could be observed in hypertension." (PMID 30906419, 2019). "For example, puerarin can have an effect on 45 targets, such as VEGFA, PTGS2, AR, PPARG, and RELA, when treating hypertension." (PMID 32265716, 2020).
Hypertension (continued). "Nevertheless, a recent metanalysis suggested an overexpression of VEGFA in subjects with MetS, hypertension, hypertriglyceridemia and hyperglycaemia, but not in relation to obesity or high LDL." (PMID 35216509, 2022). "Furthermore, these genes and proteins, along with TGFB1 and VEGFA, demonstrated significant differences between individuals with and without hypertension." (PMID 41009355, 2025). "In addition, from the point of view of the score, the score of VEGFA, ESR1 is higher, which may play an important role in the treatment of hypertension in P. ternata." (PMID 34062719, 2021).